CD47 (CD47 molecule)
Diseases named in the same sentence as CD47 in open-access papers (continued):
Sharing a sentence is not in itself a finding about the gene and the disease.
cancer (continued). "Despite widespread expression of CD47 on normal cells, CD47 blockade selectively targets cancer cells and not normal cells (except for aging red blood cells), presumably because cancer cells express prophagocytic signals that are absent from normal cells." (PMID 32281289, 2020). "Consequently, a strong enhanced antitumor effect of SG635‐SF was proved in vivo and the enhanced antitumor effect of SG635‐SF was CD47‐dependent, suggesting the potency of SG635‐SF in the treatment of CD47‐positive cancer." (PMID 31899582, 2020). "It has been shown that CD47 antibody-induced apoptosis of cancer cells is due to neither ADCC nor CDC." (PMID 33329583, 2020). "Dual blockade of CD47 and HER2 is suggested to eliminate resistant cancer cells in BC radiotherapy." (PMID 32929084, 2020). "Unlike cancers, CD47 upregulation during infection stems from cytosolic or endosomal stimulation of pattern recognition receptors." (PMID 32882841, 2020). "In addition, another anti-CD47 mAb drug phase-I study is being conducted to evaluate the safety, tolerability, and initial efficacy of IBI188 injection in patients with advanced malignant tumors and lymphomas (NCT03763149)." (PMID 33384022, 2020). "Here, we demonstrate that in fact SLAMF7 expression on cancer cells is not required and does not impact on CD47 antibody therapy." (PMID 30710089, 2019). "In this study, the authors demonstrate that SLAMF7 expressed by cancer cells is not required for phagocytosis suggesting that, in contrast to CD47 expression, SLAMF7 should not be used as selection criterion for CD47-targeted therapy." (PMID 30710089, 2019). "Therefore, we probed the proteomic data for expression pattern of other well-known cancer stem cell markers such as ALDH1A1 (2.6 fold), CD151 (2.1 fold), CD47 (1.9 fold) and THY1 (3.5 fold)." (PMID 31438645, 2019). "Apart from direct and fatal stimuli on cancer cell membrane system with CSC marker CD44 and CD133 expression level reduced, our studies have defined that GrA down-regulated the expression level and altered the distribution pattern of CD47." (PMID 31139022, 2019). "To evaluate whether synergy blocking of CD47 and CD274 on cancer cells could be effectively against CTCs in the lungs, we employed a well-established CTCs 4T1 model, which spontaneously developed lung metastasis." (PMID 30872703, 2019). "CD47 mRNA expression positively correlated with schlafen-11 mRNA expression in a subset of human cancers but not the corresponding non-malignant tissues." (PMID 31632920, 2019). "This suggested that CD47 mAb had no direct effect on cancer cell viability in the absence of macrophages." (PMID 30674867, 2019). "It has been confirmed that combination CD47 and CD274 is an excellent method for cancer therapy." (PMID 30872703, 2019). "CD47 is overexpressed in many different cancer cell types and represents an independent negative prognostic factor." (PMID 31750244, 2019). "First, we determined expression of CD47 and CD274 in mouse cancer cells." (PMID 30872703, 2019). "The CD47/SIRP-α axis has been established as an important regulator of innate anti-cancer immunity, with many if not all malignancies overexpressing the receptor CD47 that binds to phagocyte-expressed SIRP-α1–3." (PMID 30710089, 2019). "Given our data’s indication that CD47 is correlated with the differentiation of ESCC cells, we further aimed to explore whether CD47+CD133+ cancer cells were more stem‐like." (PMID 30741466, 2019). "Taken together, these data clearly demonstrate that expression of SLAMF7 on hematopoietic cancer cells is not required for phagocytosis by macrophages upon CD47 blocking therapy." (PMID 30710089, 2019). "The data presented here demonstrate that surface expression of SLAMF7 on hematopoietic cancer cells, specifically on B cell malignant cells, is not required for phagocytosis upon CD47 blocking treatment, nor upon combination treatment with rituximab." (PMID 30710089, 2019).
cancer (continued). "But CD47 seems not to be a perfect surrogate marker of CSCs, because of its high expression in majority cancer cells, including non‐CSCs, restricts the real enrichment CSCs numbers in CD47+ cells." (PMID 30741466, 2019). "We confirmed THE expression of CD47 and CD274 in a series of mouse cancer cells." (PMID 30872703, 2019). "The CD47 re-distribution on cancer cells indicated the following research about macrophage-mediated phagocytosis in CSC-targeting therapeutic approaches, leading to elimination of cancer cells in pre-clinical models." (PMID 31139022, 2019). "We show that CD47 is not modulated at different cancer stages, although patients with the lowest expression of CD47 show significant better progression-free survival, after correcting for the presence of BAP1, GNAQ, and GNA11 mutations." (PMID 31277366, 2019). "Long-term inhibition of CD47 even directly induced cancer cell apoptosis in the absence of macrophages." (PMID 31139022, 2019). "These include (but are not limited to), CD47 up-regulation, inability to properly surface expose (ecto-) ‘eat me’ signals like calreticulin (CALR), or reduction in chemotactic signals facilitating sensing of cancer cells dying through ICD by the immune cells." (PMID 29707136, 2018). "In addition, CD44 and CD47, which we found to be upregulated after ADH1B upregulation, help in metastasis by promoting cancer cells’ adhesion to peritoneum." (PMID 29861857, 2018). "Interference with CD47-SIRPα interactions has also been shown to increase ADCC by monocytes and neutrophils, making this interaction an innate immune checkpoint and an attractive target for enhancing antibody therapy in cancer." (PMID 30761158, 2018). "These well-executed studies provided important molecular insights into a potentially effective therapeutic strategy by elevating phagocytosis against cancers by targeting the PD-1 pathway with PD-L1 protein or anti-PD-1 and sensitizing CT26 cells to anti-CD47 therapy." (PMID 30062558, 2018). "Another intriguing strategy is targeting CD47, a “do not-eat-me” signal on macrophages and other antigen-presenting cells for cancer immunotherapy." (PMID 30577797, 2018). "This suggests that inflammation and the NFKB1 ‘switch' could also be involved in the upregulation of CD47 expression in other cancer types, such as T-ALL, through the activation of a different CD47 cis-regulatory region." (PMID 28378740, 2017). "The expression of CD47 on the cancer cell surface transmits “don’t eat me” signalling that not only inhibits phagocytosis of cancer cells by phagocytes but also impairs anti-cancer T cell responses." (PMID 29050218, 2017). "Perhaps the prominent CD47 protein increase and rapid transcript upregulation occurring in MCF7 cancer cells is due to the presence of the CD47 SE characterized by hyper H3K27ac (which is absent in HepG2)." (PMID 28378740, 2017). "The ubiquitous cell surface protein CD47 is up-regulated in many cancers, and its high expression is a negative prognostic indicator for several cancers including invasive breast cancer." (PMID 26840086, 2016). "CD47 has been reported to be overexpressed on the surface of cancer cells and exhibit weak or no expression on normal cells." (PMID 26318039, 2015). "Besides immunoglobulin heavy chains, T-cell receptors (such as TCR-a and TCR-b), immunoglobulin -like cell adhesion molecules (such as CD47, CD54, CD58) were also found to be expressed in cancer cells." (PMID 23133595, 2012). "Finally, although PSFL‐NK13 significantly altered the coexistence of αvβ3 and CD47 on cancer cell membranes, it did not affect FN‐induced activation of αvβ3." (PMID 41168993, 2026). "Thus, activation of αvβ3 is not essential for its coexistence with CD47 on the cancer cell membrane." (PMID 41168993, 2026).
cancer (continued). "In many cancers, the overexpression of “don’t eat me” signals—such as those mediated by the CD47–SIRPα pathway—counteracts the pro-phagocytic signal of CRT, thereby preventing phagocytosis and hindering subsequent antigen uptake, ultimately disrupting the cancer–immunity cycle." (PMID 40429961, 2025). "Mechanism investigations revealed that miR-96-5p suppressed CD47 expression by acting on the 3’-UTR (“UGCCAA”) of CD47 mRNA and encouraged macrophages to polarize to the M1 type via exosome transfer, leading to the phagocytosis and direct elimination of PDAC cancer cells." (PMID 41350707, 2025). "Further research exploring these interdisease differences could help clarify why CD47 shows prognostic significance in some cancers but not in classical HL." (PMID 40104289, 2025). "Thus, known positive and negative transcriptional regulators of CD47 mRNA expression in cancer cells have parallel effects on IFT57 mRNA expression." (PMID 39201643, 2024). "Many cancers evade attack by phagocytes through increasing CD47 expression, but it has been shown that the potent phagocytosis of low SIRPα-expressing macrophages when activated by pro-inflammatory factors is independent of CD47 expression." (PMID 40458305, 2024). "Ligand LGALS9 with its receptors (CD44, CD47, and HAVCR2) showed that the inflammatory meta program also interacted with immune cells, implying that it is a cysteine/galactose binding protein that can compromise the functions of NK and T cell to facilitate cancer cell immune escape." (PMID 38944814, 2024). "Given that certain challenges may arise when it comes to using anti-CD47 antibodies in cancer immunotherapy as apart from blocking the protein expressed on cancer cells, CD47 on non-cancerous cells including red blood cells will be blocked as well." (PMID 38892394, 2024). "Likewise, the released anti-CD47 antibody blocked the “Do not eat me” signal in cancer cells, thus increasing macrophage phagocytosis of cancer cells." (PMID 37457707, 2023). "Besides, CD47 was downregulated in LRT groups compared with LDH groups, and the combined CD47/CHOP changes will lead to the activation of the immune system against cancer cells." (PMID 37951973, 2023). "Cancer cells display higher levels of CD47 on their surface than non-malignant cells." (PMID 37822610, 2023). "However, unlike PD-L1, CD24 and CD47 protected cancer cells from attack by directly interacting with the Siglec-10 signaling pathway in macrophages." (PMID 37875918, 2023). "However, the functions and implications of CD47 in the TME of cancer patients undergoing immunotherapy are still not fully elucidated." (PMID 38188674, 2023). "The interaction of CD47 with its ligand signal regulatory protein-α (SIRPα) serves as a marker of self to innate immune cells like macrophages, which engulf foreign cells but not self, and, in this way, CD47 expression protects cancer cells from phagocytic clearance." (PMID 36960054, 2023). "In addition, a significant upregulation of CD47 in CTCs plays a potential role in immune escape and thus may also promote the spread of CRC and enhances the stemness of cancer cells." (PMID 36902476, 2023). "Furthermore, CD47 functions as a dominant macrophage checkpoint, providing a potent “do not eat me” signal to enable cancer cells to evade the innate immune system." (PMID 37189735, 2023). "However, favoring M1 is not enough; reducing the expression of CD47 on CSCs, providing an opsonizing agent, and targeting CSCs at the same time are crucial for effective cancer treatment." (PMID 38035101, 2023). "Combining temozolomide (a chemotherapeutic agent) and CD47 blocking agents, including antagonistic anti-CD47 monoclonal antibody (mAb) increases type 1 IFN production by activating cGAS/STING signaling in myeloid antigen-presenting cells (APCs)/MICs in different cancers." (PMID 37380989, 2023).
cancer (continued). "Blocking the CD47-SIRPα interaction may therefore potentiate neutrophil-mediated antibody-dependent cellular cytotoxicity (ADCC) towards cancer cells, and various inhibitors of the CD47-SIRPα axis are now in clinical studies." (PMID 35884427, 2022). "In addition, CD47 overexpression by cancer cells was directly related to SIRPα expression by TAMs and not with CD68+ TAMs, showing that an interplay between CD47 expressing cancer cells and the SIRPα+ Μφ exists in NSCLC." (PMID 35406573, 2022). "We performed an additional in silico analysis of TIM3, LAG3, TIGIT, B7-H6 and CD47-SIRPa to explore the correlation of these markers of immunomodulation in situ by using the online platform TIMER, which is based on 10,897 samples across 32 cancer types from The Cancer Genome Atlas (TCGA)." (PMID 33805268, 2021). "We used a CRISPR strategy to knock out CD47 in these cancer stem cells and, remarkably, found no viable CD47-null colonies could be obtained." (PMID 33925464, 2021). "CD47 presents as a “do not eat me” signal to APCs and is overexpressed in many cancer cells." (PMID 34579759, 2021). "Furthermore, in cancers resistant to CD47 blockade, anti-CD24 mAb enhance the phagocytic ability of macrophages, indicating there is a synergistic effect between CD24 interference and anti-CD47/SIRPα treatment." (PMID 34625124, 2021). "In line with this, when activated, bone marrow-derived macrophage (BMDMs) obtained from Sirpα−/− mice displayed a strong capacity to phagocytize CD47-expressing MC38 cancer cells, whereas BMDMs from WT mice failed to engulf cancer cells under the same treatment." (PMID 34050181, 2021). "Despite the fact that many cancers exploit this mechanism through increasing CD47 expression, and thereby evade attack by phagocytes, we previously found that mere depletion of the CD47-SIRPα axis or SIRPα-mediated inhibitory signaling does not lead to phagocytosis." (PMID 34050181, 2021). "Notably, CD47-mediated phagocytosis also did not depend on cancer cell expression of the pro-phagocytic molecule SLAMF7 in an earlier paper." (PMID 33105656, 2020). "Dual blocking CD47 and HER2 may effectively abolish resistant cancer cells in BC radiotherapy." (PMID 32929084, 2020). "According to our analysis, while CD47 blockade may be effective across many, if not all, cancer histologies, the patients most likely to benefit will be those with the highest surface expression of this marker." (PMID 35582455, 2020). "Thus, expression of SLAMF7 on cancer cells is not a requisite for phagocytosis upon CD47 antibody treatment." (PMID 30710089, 2019). "Next, we evaluated whether phagocytic activity of a clinically relevant CD47 targeting antibody might similarly be independent of SLAMF7 expression on cancer cells." (PMID 30710089, 2019). "Anti-CD47 and anti-CD274 could blockade CD47 and CD274 expression on 4T1 cancer cells." (PMID 30872703, 2019). "In conclusion, mRNA and/or protein expression levels of SLAMF7 on hematopoietic cancer cells should not be used as selection/exclusion criterion for future clinical studies that evaluate the therapeutic potential of CD47-blockade or the combination with CD47 blocking therapy." (PMID 30710089, 2019). "However, SLFN11 promoter methylation is independent of CD47 expression in some cancer types that exhibit a positive correlation between SLFN11 and CD47 mRNA expression." (PMID 31632920, 2019). "The transcriptomic levels of CD47 were not significantly different between cancer stages." (PMID 31277366, 2019). "In addition, CD47 is expressed on high levels on cancer stem cells (CSCs), but not on normal cells in the pancreas." (PMID 30809507, 2019). "Similarly, M2-like MDMs also phagocytosed more cancer cells than M1-like MDMs but, unlike M1-like MDMs, were insensitive to anti-CD47 opsonization." (PMID 30760760, 2019).
cancer (continued). "For instance, ligation of CD47 with TSP-1, a glycoprotein derived from megakaryocytes, which is increased in MF and causes activation of TGF-β, can induce proliferation of some cancer cells, such as astrocytoma cells, but not of their normal counterparts." (PMID 30539968, 2018). "Thus, CD47 antibody effectively detected CD47 antigen demonstrating variable CD47 expression in different cancer cell lines that was in most cases higher than in non-cancerous cell lines such as keratinocytes and 293 cells." (PMID 29065481, 2017). "For the surprising outcomes, it is conceivable that the recombinant CD47 used in blocking assays may not be structurally identical to the natural CD47 on cancer cell surface considering differences in modification." (PMID 27863402, 2016). "Currently, we could not rule out the possibility that recombinant CD47 may not be the best surrogate for natural CD47 on cancer cell surface." (PMID 27863402, 2016). "Our data support the usage of PPRHs to diminish CD47/SIRPα interaction by decreasing the expression of both molecules thus resulting in an enhanced killing of MCF-7 cells by macrophages, which might translate into beneficial effects in cancer therapy." (PMID 27671753, 2016). "Importantly, PSFL‐NK13 did not affect the expression of SIRPα protein on macrophage membranes (control vs 4 μm PSFL‐NK13, p = 0.3992), reinforcing its specificity for CD47/αvβ3 interactions on cancer cell membranes without impacting SIRPα on macrophage membranes." (PMID 41168993, 2026). "However, as CD47 is also expressed on noncancerous cells, such as platelets and red blood cells, delivering this antibody locally via our gel, rather than systemically, is advantageous to avoid known on‐target‐off‐cancer toxicities." (PMID 39553428, 2024). "Therefore, the interplay between CD47 and CALR underscores their integral roles in modulating immune responses and presents promising avenues for therapeutic strategies, which should be oriented to selectively upregulate CALR and quench CD47 signaling on cancer cells." (PMID 39767726, 2024). "Consequently, blocking CD47 could potentially increase the ability of CD8+ T cells to detect cancer neoantigens presented by the MHC I complex, thereby promoting an adaptive immune response against the cancer cells." (PMID 38690738, 2024). "Thus, in primary noncancer and cancer cells, CD47 restrains growth." (PMID 38362603, 2024). "Based on evidence for primary cilium functions in multiple cancers and the correlations between IFT57 expression and survival in several cancers, targeting the IFT57 and CD47 axes together may enhance the efficacy of the CD47-specific therapeutics currently in clinical trials." (PMID 39201643, 2024). "Additionally, a portion of cancer patients do not respond to CD47-targeting therapy." (PMID 38773982, 2024). "Several signaling pathways have been identified that mediate the increased CD47 expression in specific cancers, but the possibility has not been considered that transcription regulators interacting with the promoter region of CD47 may simultaneously regulate expression of the adjacent IFT57." (PMID 39201643, 2024). "Hence, chronic activation of the DNA damage response pathway in cancer cells, augments a general phenomenon seen in non-malignant cells, and may contribute to constitutive elevated expression of CD47 in human tumors leading to immune evasion." (PMID 36882648, 2023). "Because we observed detectable surface SIRPγ protein expression in less than 10% of A549 and H1975 cells cultured under standard conditions, comprising the CSLC populations, we were puzzled to account for how SIRPγ might control CD47 expression by the large majority of (non-stem) cancer cells." (PMID 35229723, 2022). "However, how CD47 expression in cancer cells is regulated has not been well understood." (PMID 35229723, 2022).